GAREM1 (GRB2 associated regulator of MAPK1 subtype 1)
Description:
[Isoform 1]: Acts as an adapter protein that plays a role in intracellular signaling cascades triggered either by the cell surface activated epidermal growth factor receptor and/or cytoplasmic protein tyrosine kinases. Promotes activation of the MAPK/ERK signaling pathway. Plays a role in the regulation of cell proliferation.
Synonyms: C18orf11; FAM59A; GAREM; FLJ21610; Gm944
Tractability: Antibody: its Gene Ontology location is reachable by antibodies, with medium confidence. PROTAC: its protein half-life has been measured.
Gene: Protein-coding gene on chromosome 18 (32,124,877 to 32,470,882, reverse strand). Ensembl gene ENSG00000141441.
Subcellular location (Human Protein Atlas): Nucleoplasm; Cytosol
Gene Ontology:
Molecular function: proline-rich region binding; protein binding
Biological process: cellular response to epidermal growth factor stimulus; epidermal growth factor receptor signaling pathway; positive regulation of cell population proliferation; positive regulation of ERK1 and ERK2 cascade
Cellular component: plasma membrane
Genetic constraint (gnomAD): Loss-of-function variants: 26 observed, 71.18 expected, observed/expected ratio (o/e) 0.37, 90% interval 0.27 to 0.51. The upper end of that interval is the gene's LOEUF score, 0.51, which puts it in group 2 of 6, group 1 being the genes least tolerant of losing a copy. Missense variants: 1,026 observed, 1,135.7 expected, observed/expected ratio (o/e) 0.9, 90% interval 0.86 to 0.95. Synonymous variants: 440 observed, 444.72 expected, observed/expected ratio (o/e) 0.99, 90% interval 0.91 to 1.07.
Homologues: Orthologues: chimpanzee GAREM1 (99% identical), macaque GAREM1 (98% identical), dog GAREM1 (94% identical), rabbit GAREM1 (93% identical), pig GAREM1 (92% identical), rat Garem1 (92% identical), mouse Garem1 (91% identical), guinea pig GAREM1 (90% identical), tropical clawed frog mcm3 (78% identical), zebrafish garem (63% identical). Paralogues in human: GAREM2 (44% identical).
Diseases named in the same sentence as GAREM1 in open-access papers:
GAREM1 is named in the same sentence as 5 diseases in open-access papers, as found by Europe PMC text mining. Sharing a sentence is not in itself a finding about the gene and the disease. The quoted sentences say what the papers report.
tumor (1 paper, 2025). "Notably, GAREM1 is known to activate the RAS/RAF/MAPK pathway and is implicated in tumor development." (PMID 41250218, 2025).
GAREM1 also shares sentences with these, for which no sentence is quoted: Huntington disease (1 paper); malignant tumors (1); neuroblastoma (1); rheumatoid arthritis (1).